SMAD7 (SMAD family member 7)
Description:
Antagonist of signaling by TGF-beta (transforming growth factor) type 1 receptor superfamily members; has been shown to inhibit TGF-beta (Transforming growth factor) and activin signaling by associating with their receptors thus preventing SMAD2 access. Functions as an adapter to recruit SMURF2 to the TGF-beta receptor complex. Also acts by recruiting the PPP1R15A-PP1 complex to TGFBR1, which promotes its dephosphorylation. Positively regulates PDPK1 kinase activity by stimulating its dissociation from the 14-3-3 protein YWHAQ which acts as a negative regulator.
Synonyms: MADH7; MADH8; CRCS3
Tractability: Antibody: its Gene Ontology location is reachable by antibodies, with high confidence. PROTAC: UniProt records ubiquitination sites on it; ubiquitination databases record sites on it.
Gene: Protein-coding gene on chromosome 18 (48,919,853 to 48,952,020, reverse strand). Ensembl gene ENSG00000101665.
Subcellular location: Nucleus; Cytoplasm
Subcellular location (Human Protein Atlas): Basal body; Centrosome; Nucleoplasm; Cytosol; Nucleoli fibrillar center
Pathways (Reactome):
Signal Transduction: Downregulation of SMAD2/3:SMAD4 transcriptional activity; Downregulation of TGF-beta receptor signaling; SMAD2/SMAD3:SMAD4 heterotrimer regulates transcription; Signaling by BMP
Metabolism of proteins: UCH proteinases; Ub-specific processing proteases
Immune System: Interferon gamma signaling
Gene Ontology:
Molecular function: activin receptor binding; beta-catenin binding; I-SMAD binding; protein binding; transcription corepressor activity; transcription regulator inhibitor activity; type I transforming growth factor beta receptor binding; ubiquitin protein ligase binding; ubiquitin-like ligase-substrate adaptor activity; collagen binding
Biological process: adherens junction assembly; beta-catenin destruction complex disassembly; negative regulation of activin receptor signaling pathway; negative regulation of BMP signaling pathway; negative regulation of SMAD protein signal transduction; negative regulation of transcription by RNA polymerase II; negative regulation of transforming growth factor beta receptor signaling pathway; positive regulation of cell-cell adhesion mediated by cadherin; protein stabilization; protein-containing complex disassembly; protein-containing complex localization; regulation of epithelial to mesenchymal transition; response to laminar fluid shear stress; SMAD protein signal transduction; transforming growth factor beta receptor signaling pathway; anatomical structure morphogenesis; artery morphogenesis; cell differentiation; negative regulation of cell migration; negative regulation of epithelial to mesenchymal transition; negative regulation of T cell cytokine production; negative regulation of T-helper 17 cell differentiation; negative regulation of T-helper 17 type immune response; positive regulation of proteasomal ubiquitin-dependent protein catabolic process; regulation of cardiac muscle contraction; and 13 more
Cellular component: adherens junction; cytoplasm; cytosol; fibrillar center; nucleoplasm; nucleus; plasma membrane; protein-containing complex; chromatin; heteromeric SMAD protein complex; transcription regulator complex
Genetic constraint (gnomAD): Loss-of-function variants: 7 observed, 29.98 expected, observed/expected ratio (o/e) 0.23, 90% interval 0.13 to 0.44. The synonymous counts are far from expectation, so gnomAD's model fits this gene poorly and the ratio says little. Missense variants: 448 observed, 501.72 expected, observed/expected ratio (o/e) 0.89, 90% interval 0.83 to 0.97. Synonymous variants: 309 observed, 233.44 expected, observed/expected ratio (o/e) 1.32, 90% interval 1.21 to 1.45.
Gene-disease validity (ClinGen):
ClinGen rates the evidence that SMAD7 causes each of these diseases.
congenital heart disease (autosomal dominant): Limited. A heart disease that is present at birth.
Homologues: Orthologues: macaque SMAD7 (99% identical), chimpanzee SMAD7 (99% identical), pig SMAD7 (98% identical), mouse Smad7 (98% identical), rat Smad7 (98% identical), dog SMAD7 (97% identical), rabbit SMAD7 (92% identical), tropical clawed frog smad7 (76% identical), zebrafish smad7 (71% identical), guinea pig SMAD7 (52% identical), Drosophila melanogaster Dad (31% identical), Caenorhabditis elegans tag-68 (19% identical), and 1 more. Paralogues in human: SMAD6 (50% identical), SMAD1 (27% identical), SMAD9 (27% identical), SMAD5 (26% identical), SMAD2 (25% identical), SMAD4 (25% identical), SMAD3 (24% identical).
Diseases named in the same sentence as SMAD7 in open-access papers:
SMAD7 is named in the same sentence as 256 diseases in open-access papers, as found by Europe PMC text mining. Sharing a sentence is not in itself a finding about the gene and the disease. The quoted sentences say what the papers report.
renal fibrosis (105 papers, 2005 to 2026). A final common manifestation of a wide variety of chronic kidney diseases characterized by glomerulosclerosis and tubulointerstitial fibrosis. "The downregulation of SMAD7 can enhance renal fibrosis and inflammation, potentially increasing susceptibility to diabetic nephropathy, a major complication of T1DM." (PMID 40041782, 2025). "In term of renal fibrosis, Smad3 is pathogenic and overreactive, whereas Smad7 is protective but lost in the fibrotic kidney." (PMID 35541902, 2022). "In the context of renal fibrosis, Smad3, a key downstream of mediator, is pathogenic, but Smad7, a negative regulator of Smad3, is protective 4-6." (PMID 36147472, 2022). "Conversely, Smad7-deficient diabetic mice exhibited more severe renal fibrosis, albuminuria, and inflammation compared with those with a normal genotype." (PMID 32215042, 2020). "The activation or inactivation of TGF-β/Smad signaling pathway, as reflected by the expression levels of Smad2, Smad3 and Smad7, is a pathogenic mechanism in the progression of renal fibrosis." (PMID 30101622, 2018). "Overexpression of the inhibitory Smad7 results in inhibition of renal fibrosis, while loss of renal Smad7 enhances TGF-β/Smad3-mediated renal fibrosis and inflammation." (PMID 29039786, 2017). "Mice deficient in SMAD7 have increased susceptibility to renal fibrosis, whereas those with overexpression of SMAD7 have attenuated fibrosis." (PMID 29114233, 2017). "Enhanced renal injury in Smad7 KO mice was associated with more progressive renal fibrosis with elevated TGF-β/Smad3 signalling." (PMID 23301086, 2013). "Smad7-deficient mice developed more severe diabetic kidney injury, characterized by a significant increase in microalbuminuria, renal fibrosis and inflammation." (PMID 22204639, 2011). "In STZ-induced DN and db/db mice-associated DN, Smad7 knockout mice develop more severe albuminuria, renal fibrosis (glomerulosclerosis, tubulointerstitial ECM production), and inflammation (macrophage infiltration, expression of inflammatory cytokines such as TNF-α, IL-1β, and MCP-1)." (PMID 34360646, 2021). "In addition, the loss of Smad7 expression also largely promotes TGF-β1-induced renal fibrosis and Smurf2/NF-κB-driven inflammation in mouse models of obstructive nephropathy and angiotensin II-induced hypertensive nephropathy 27-30." (PMID 34512167, 2021). "Smad7‐deficient mice were more susceptible to renal fibrosis, but Smad7 overexpression could alleviate the fibrotic process in vitro." (PMID 32253812, 2020). "In the context of DN, TGF-β/Smad3 signaling is highly activated, which is associated with downregulation of renal Smad7, resulting in renal fibrosis as seen in both experimental and human diabetic kidneys and in vitro under high glucose and advanced glycation end products conditions." (PMID 24646636, 2014). "Further studies revealed that inhibition of renal fibrosis in CHYS-treated diabetic rats was associated with inhibition of TGF-β1/Smad3 signaling as demonstrated by upregulation of Smad7 but downregulation of TGF-β1, TGF-β receptors, activation of Smad3, and expression of miRNA-21." (PMID 24646636, 2014). "Taken together, the present study revealed that enhanced Sp1-TGF-β1/Smad3-NF-κB signaling and loss of miR-29 may be mechanisms by which deletion of Smad7 promotes ANG II-mediated renal fibrosis and inflammation." (PMID 23301086, 2013). "Outcomes from this study suggested that restoring the balance of downstream TGF-β/Smad signaling with AA (a Smad7 agonist) and NG (a Smad3 inhibitor) may represent a new therapeutic approach for chronic kidney disease associated with progressive renal fibrosis." (PMID 26474462, 2015). "Our results revealed that PP ameliorated renal fibrosis by upregulating the expression of Smad7 and inhibiting the activation of TGFβ‐Smad2/3 signal pathway in kidneys from db/db mice." (PMID 40688601, 2025).
renal fibrosis (continued). "While Smad2-4 are activated by TGF-β1 to drive renal fibrosis, Smad7, an inhibitory Smad, counteracts the process of renal fibrosis by suppressing the expression of fibrotic cytokines." (PMID 40510419, 2025). "Multiple studies have demonstrated that miR-21-5p functions as a critical mediator of TGF-β–induced renal fibrosis, both by targeting Smad7, a negative regulator of the pathway, and by modulating PTEN/AKT and ERK/MAPK cascades 71,72." (PMID 41407811, 2025). "Abnormal expression of TGF-β1 can induce renal fibrosis through the classical Smad pathway, in which Smad3 increases fibrin transcription and promotes tissue fibrosis, while Smad7 inhibits tissue fibrosis." (PMID 39371929, 2024). "Studies have shown that activation of FXR can inhibit the activation of TGF-β1 pathway by down-regulating the expression of Smad3 and up-regulating the expression of Smad7, thereby alleviating renal fibrosis." (PMID 39371929, 2024). "In future studies, we intend to undertake more experiments to explore the specific mechanism of EVL binding to Smad7 that regulates TGF‐β1/Smad signal transduction in renal fibrosis." (PMID 37537731, 2023). "The overexpression of Smad7 has been shown to be a therapeutic agent for renal fibrosis in various models of kidney diseases." (PMID 37179292, 2023). "Smad7 was discovered in renal tubular epithelial cells (RTECs) during the inhibition of renal fibrosis." (PMID 36675720, 2022). "Results showed that overexpression of Smad7 blocked both renal fibrosis and inflammatory pathways in terms of Smad2/3 and NF-B activation, respectively (p<0.01)." (PMID 36128207, 2022). "According to studies, SMAD7 can prevent renal fibrosis and inflammation by preventing the activation of nuclear factor-kB (NF-kB) and TGF-β1/SMAD signalling pathways." (PMID 36428551, 2022). "In contrast, AANG preventive treatment significantly enhanced renal Smad7 expression, resulting in inhibition of renal fibrosis by reducing collagen I and α-SMA expression in the diabetic kidney of db/db mice." (PMID 36147472, 2022). "In conclusion, we showed that RDV inhibits renal fibrosis in obstructed kidneys, which is correlated with reduced phosphorylation of Smad3 and increased expression of Smad7." (PMID 34276356, 2021). "In this context, Smad7 has been shown to suppress renal fibrosis by down-regulating pro-fibrotic miRNAs such as miR-21 and miR-192 while up-regulating the anti-fibrotic miR-29b." (PMID 34095153, 2021). "It plays an important role in mediating renal fibrosis by enhancing Smad7 degradation, Smad3 phosphorylation, and TGF-β receptor 1 expression." (PMID 34059951, 2021). "It has been reported that Arkadia can induce Smad7 degradation and thus enhance the renal tubular epithelial-to-mesenchymal transition and renal fibrosis in a rat unilateral ureteral obstruction model 32,33." (PMID 34512167, 2021). "By contrast, disruption of Smad7 aggravates renal fibrosis in the UUO kidney, aristolochic acid nephropathy, and hypertensive nephropathy." (PMID 34360646, 2021). "Smad ubiquitination regulatory factor 2 (Smurf2), a ubiquitin ligase for Smad, plays a key regulatory role in the TGF-β signaling pathway during renal fibrosis, which is mainly dependent on the degradation of ubiquitinated Smad7 and Smad2." (PMID 34059951, 2021). "The central role for Smad7 in CRS was demonstrated in a Smad7 deficiency model, which resulted in enhanced ANG II‐induced loss of miR‐29b expression and the promotion of murine cardiac and renal fibrosis through activation of TGF‐β/Smad3 and NF‐kB signaling." (PMID 33529442, 2021). "Smad7 overexpression can improve renal fibrosis by increasing the expression of miRNA-29 and inhibiting the levels of miRNA-192 and miRNA-21 in obstructive nephropathy kidney cells." (PMID 34059951, 2021).
renal fibrosis (continued). "Although the overexpression of TGF-β plays an important role in the development of renal fibrosis, the levels of SMAD7 protein had decreased in unilateral ureteral obstruction kidneys compared to placebo-surgery control kidneys in mouse models." (PMID 34059951, 2021). "Similar results were demonstrated in other studies on myocardial fibrosis, CCl4-induced model to HSC-T6 cell lines, and renal fibrosis, in which miR-17-5p regression has been correlated with fibrosis amelioration via upregulation of the protective Smad-7." (PMID 34778375, 2021). "The activation of Smad7 in the rat kidney tubular epithelial cell (TEC) line (NRK52E) is known to contribute to TGF-mediated renal fibrosis." (PMID 34059951, 2021). "Another mechanism used by miR-21 to stimulate renal fibrosis is the inhibition of Smad7 protein, a negative regulator of TGF-β1/Smad3 signaling." (PMID 34095153, 2021). "As overexpression of Smad7 inhibits renal fibrosis and inflammation but also induces apoptosis in podocytes, thus, overexpression of PRINS upregulates Smad7 expression and promotes apoptosis in mouse podocytes." (PMID 33574750, 2020). "In contrast, Erbb4-IR is another novel Smad3-dependent lncRNA capable of inhibiting renal fibrosis by targeting miR-29b and Smad7 in both obstructive nephropathy and type II diabetic nephropathy, respectively." (PMID 32258028, 2020). "We also find that Ang II can induce an E3‐ligase, Smurf2, which can bind and degrade Smad7, thereby promoting Smad3‐dependent renal fibrosis and NF‐κB‐mediated renal inflammation." (PMID 32971570, 2020). "In contrast, overexpression of Smad7 suppresses both renal fibrosis and inflammatory in these disease models, making Smad7 as an promising therapeutic strategy for CKD." (PMID 32258028, 2020). "Using rat pTECs, they demonstrated that TGF-β promoted renal fibrosis by inducing miR-21 which in turn targets Smad7 and PTEN, the negative regulators of Smad3 and PI3K, respectively." (PMID 33364960, 2020). "Present results, therefore, support the notion that TGF‐β/Smad‐related proteins p‐Smad2 as well as p‐Smad3 are up‐regulated, whereas Smad7 expression decreased in renal fibrosis models compared with that in the controls." (PMID 32253812, 2020). "This study also identified Erbb4-IR as responsible for TGF-β/Smad3-mediated renal fibrosis by downregulating Smad7." (PMID 32295041, 2020). "Mir-21 has been shown to aggravate diabetes-induced renal fibrosis by suppressing the expression of Smad7 and PTEN." (PMID 32215042, 2020). "The TGF-β/Smad network plays an important role in renal fibrosis, and Smad7 has been shown to be a therapeutic agent for renal fibrosis in various models of kidney diseases." (PMID 32606425, 2020). "Once Smad7 is degraded through the ubiquitin proteasome degradation mechanism, Smad2/3 is activated, and renal fibrosis is enhanced." (PMID 30713574, 2019). "Downregulated expression of Smad7 was reported to endorse TGF-β1-mediated renal fibrosis and inflammation." (PMID 31022990, 2019). "It was reported that overexpression of SMAD7 inhibited renal fibrosis in diabetic kidney and in an obstructed kidney model, while a SMAD7 gene deletion promoted renal fibrosis." (PMID 30150520, 2018). "Dysregulation of Smad7 promotes renal fibrosis and conversely Smad7 treatment substantially attenuating progressive kidney diseases via inactivating TGF-β/Smad3 signaling." (PMID 30524310, 2018). "EZH2 was shown to play an important role in the development of renal fibrosis by downregulating expression of Smad7 and PTEN to activate profibrotic signaling pathways." (PMID 27823969, 2016). "It was demonstrated that miR-21 overexpression or Smad7 knockdown ends with more severe renal fibrosis." (PMID 27610006, 2016). "miR-21-dependent targeting PTEN and Smad7 was also found to be responsible for the progression of renal fibrosis in human diabetic nephropathy." (PMID 27610006, 2016).